SLC35G6 (solute carrier family 35 member G6)
Synonyms: AMAC1L3; TMEM21B
Tractability: Antibody: UniProt predicts a signal peptide or a membrane-spanning region.
Gene: Protein-coding gene on chromosome 17 (7,481,446 to 7,483,496, forward strand). Ensembl gene ENSG00000259224.
Subcellular location: Membrane
Gene Ontology:
Cellular component: membrane
Genetic constraint (gnomAD): Loss-of-function variants: 18 observed, 19.4 expected, observed/expected ratio (o/e) 0.93, 90% interval 0.64 to 1.38. The synonymous counts are far from expectation, so gnomAD's model fits this gene poorly and the ratio says little. Missense variants: 372 observed, 430.98 expected, observed/expected ratio (o/e) 0.86, 90% interval 0.79 to 0.94. Synonymous variants: 156 observed, 202.6 expected, observed/expected ratio (o/e) 0.77, 90% interval 0.68 to 0.88.
Homologues: Orthologues: chimpanzee SLC35G6 (96% identical), macaque SLC35G6 (91% identical), dog SLC35G6 (88% identical), mouse Slc35g3 (82% identical), rat Slc35g3 (81% identical), Drosophila melanogaster CG5281 (14% identical). Paralogues in human: SLC35G5 (93% identical), SLC35G3 (92% identical), SLC35G4 (91% identical), SLC35G2 (29% identical), SLC35G1 (18% identical).
Diseases named in the same sentence as SLC35G6 in open-access papers:
SLC35G6 is named in the same sentence as 3 diseases in open-access papers, as found by Europe PMC text mining. Sharing a sentence is not in itself a finding about the gene and the disease. The quoted sentences say what the papers report.
endometriosis (2 papers, 2020 to 2024). The growth of functional endometrial tissue in anatomic sites outside the uterine body. "SLC35G6 was identified as a susceptibility marker for migraine and endometriosis, but there are no independent replication studies and there is no strong implication of organic cation transport in the pathophysiology of these two diseases." (PMID 39098524, 2024). "The SLC35G6 gene is well expressed in the testis, lowly expressed in the endometrium and adrenal gland; however, information about its biological functions is limited; hence, further investigation into the gene and its involvement in endometriosis and migraine is necessitated." (PMID 32121467, 2020). "Combining gene-based p-values across endometriosis and migraine, three genes, two (TRIM32 and SLC35G6) of which are at novel loci, were genome-wide significant." (PMID 32121467, 2020). "Two of these genes (TRIM32, and SLC35G6) have not previously been reported for endometriosis or migraine, nor were they located on or near previously identified loci for any of the two traits—indicating that they represent novel genes and susceptibility loci for both endometriosis and migraine." (PMID 32121467, 2020). "After combining gene-based p-values across endometriosis and migraine GWAS, we found that three genes (ARL14EP, TRIM32, and SLC35G6), were genome-wide significant." (PMID 32121467, 2020). "The remaining two genome-wide significant genes, TRIM32 and SLC35G6, have not been previously reported for endometriosis or migraine, neither are they located at or near established loci for any of the two disorders; hence, they represent two novel genes and susceptibility loci for the two traits." (PMID 32121467, 2020).
SLC35G6 also shares sentences with these, for which no sentence is quoted: migraine (2 papers); lymphomatous (1).